IRF8 (interferon regulatory factor 8)
Diseases named in the same sentence as IRF8 in open-access papers (continued):
Sharing a sentence is not in itself a finding about the gene and the disease.
metastatic tumor (2 papers, 2012 to 2019). "Survival outcomes of patients with primary or metastatic disease could be stratified on the basis of IRF8 levels by macrophages." (PMID 31221219, 2019). "Our key findings that IRF8 expression by TAMs within both primary and metastatic disease was a better prognostic indicator of survival than TAM infiltration suggests that the behavior of TAMs can be represented by the status of master or major transcriptional regulators." (PMID 31221219, 2019). "Moreover, the magnitude of IRF-8 enhancement was greater in the primary tumor compared to the metastatic tumor, which also mirrored what we observed in the CMS4 system." (PMID 23028998, 2012).
mycobacterial infections (2 papers, 2015 to 2024). "Our findings may explain the susceptibility to mycobacteriosis of individuals with genetic IRF8 variants that produce deficiencies in macrophage numbers, e.g., loss-of-function IRF8 mutations." (PMID 26159717, 2015). "Mutations in the STAT1, JAK1, IRF8, SPPL2A, NEMO, and CYBB genes are responsible for phagocytic defects leading to susceptibility to mycobacterial infections." (PMID 38535546, 2024). "AD IRF8 deficiency leads to an absence of myeloid dendritic cells and susceptibility to mycobacterial infections." (PMID 38535546, 2024).
neuropathic pain (2 papers, 2020). Chronic pain caused by damage to nerve fibers. "Interferon regulatory factor 8 (IRF8) is involved in the pathogenesis of neuropathic pain." (PMID 33335768, 2020). "Hence, targeting IRF8 may be a promising therapeutic strategy for 2 Hz EA treatment of neuropathic pain." (PMID 32351637, 2020). "In summary, the present experiment demonstrated that the upregulation of IRF8 and CX3CR1 expressions as well as microglial activation in the spinal cord contributed to SNI-induced neuropathic pain." (PMID 32351637, 2020). "Hence, this experiment further confirmed that the upregulation of spinal IRF8 induced by SNI may play a crucial role in activating microglia, and its interaction with microglial activation led to SNI-induced neuropathic pain." (PMID 32351637, 2020).
neutropenia (2 papers, 2017 to 2021). A decrease in the number of neutrophils found in the blood. "Thus, our results support the notion that BCR-ABL suppresses IRF8 at the hematopoietic progenitor stages not only to impede cDC development, but also to promote neutropenia in CML." (PMID 34508131, 2021).
osteoarthritis (2 papers, 2020 to 2023). A noninflammatory degenerative joint disease occurring chiefly in older persons, characterized by degeneration of the articular cartilage, hypertrophy of bone at the margins and changes in the synovial membrane. "Based on the previous study, we then evaluate the expression distribution of the MMP, VEGFA, SPI1, and IRF8 in synovial tissues of patients with osteoarthritis." (PMID 36960385, 2023). "The single-cell RNA sequencing analysis was used to evaluate the expression distribution of the MMP, VEGFA, SPI1, and IRF8 in synovial tissues of patients with osteoarthritis." (PMID 36960385, 2023). "The expression of MMP-13 increased through stimulation by CCL20 and interferon regulatory factor-8 (IRF-8) in chondrocytes derived from patients with osteoarthritis." (PMID 32189997, 2020).
peripheral nerve injury (2 papers, 2018 to 2020). Injury to a peripheral nerve. "It was found that IRF8 expression was significantly upregulated from day 1, peaked on day 3, and the enhancement of IRF8 lasted for several weeks following peripheral nerve injury." (PMID 32351637, 2020).
primary biliary cholangitis (2 papers, 2018 to 2023). Primary biliary cholangitis (PBC) is a chronic and slowly progressive cholestatic liver disease of autoimmune etiology characterized by injury of the intrahepatic bile ducts that may eventually lead to liver failure. "In addition, high-throughput genetic studies of primary biliary cirrhosis (PBC) associated IRF5 and IRF8 with the pathogenicity of autoimmune liver diseases." (PMID 29531645, 2018).
prion disease (2 papers, 2014 to 2020). A transmissible disease that is caused by a protein that is able to induce abnormal folding of normal cellular proteins, leading to characteristic spongiform brain changes, which are associated with neuronal loss without an inflammatory response. "The transcription factors RUNX1 and IRF8, involved in the proliferation and lineage commitment of microglia, were found to be upregulated in animals with prion disease, with no differential effect of the CCR2−/− background." (PMID 24648328, 2014).
pulmonary tuberculosis (2 papers, 2011 to 2013). A bacterial infection that affects the lungs and is caused by Mycobacterium tuberculosis. "IRF8 mutant mice are susceptible to a number of intracellular infections including pulmonary tuberculosis." (PMID 21731497, 2011). "Furthermore, inactivating mutations in several of these common genes including Irf8, Irf1, and Irgm1 cause susceptibility to pulmonary tuberculosis, while conveying some degree of protection against ECM." (PMID 23853600, 2013). "IRF8 and IFNγ are required for protection against pulmonary infection with M. tuberculosis, and mice bearing mutations in either gene are hyper-susceptible to pulmonary tuberculosis." (PMID 21731497, 2011). "This list shows a 43% overlap with our list of IRF8 binding peaks, a 21% overlap with our list of genes regulated by IFNγ/CpG in a IRF8-dependent fashion, and 70% overlap with the list of genes differentially regulated during pulmonary tuberculosis in vivo." (PMID 21731497, 2011). "Although IRF8-dependent activation of pro-inflammatory pathways in myeloid cells has detrimental and pathological consequences during PbA infection, it clearly plays a protective role in other infections including pulmonary tuberculosis." (PMID 23853600, 2013). "Moreover, we observed that Ciita expression is tightly regulated by IFNγ/CpG in an IRF8-dependent fashion in macrophages from F2 mice (2×2 interaction Anova analysis), and is also regulated in pulmonary tuberculosis." (PMID 21731497, 2011).
renal carcinoma (2 papers, 2017 to 2019). A carcinoma arising from the epithelium of the renal parenchyma or the renal pelvis. "Notably, IRF8 methylation was associated with tumor grade in renal cancer." (PMID 28388578, 2017). "Based on existing data in renal cancer, we hypothesized that IRF8 might suppress cell growth by modulating the cell cycle and apoptosis." (PMID 28388578, 2017). "Our data showed that IRF8 performed as a candidate tumor suppressor by inducing G2/M phase cell cycle arrest and apoptosis in MDA-MB-231 and T47D cells, consistent with the function of IRF8 in renal cancer, and also by inhibiting cell migration and invasion in MDA-MB-231, but not in T47D cells." (PMID 28388578, 2017).
retinal (2 papers, 2021 to 2022). "However, under pathological conditions, Irf8 is crucial for the transformation of resident microglia into a reactive phenotype and thus for the suppression of retinal inflammation and CNV formation." (PMID 34544421, 2021).
retinal disease (2 papers, 2021 to 2022). "This highlights the importance of IRF8 and retinal MG for the development of pathological neovascularisation in the eye and highlights the potential of immunomodulatory therapeutic interventions of rMG recruitment in retinal disease." (PMID 34544421, 2021).
rosacea (2 papers, 2021 to 2022). A chronic erythematous skin disorder that affects the face. "Consistently, by immunohistochemistry we verified the increased nuclear localization of phosphor-STAT1, IRF1 and IRF8 in both epidermis and dermal infiltration of rosacea lesions." (PMID 34290700, 2021). "Further verification of the GSE65914 and GSE125733 datasets was performed, and STAT1, which is involved in the regulation of three hub genes (IRF1, IRF8, and CXCL10), was found to be differentially expressed in FFA and rosacea." (PMID 36091020, 2022). "In addition, we identified the critical role of IRF1 and IRF8 in FFA and rosacea and the high expression of STAT1 in this study." (PMID 36091020, 2022).
schizophrenia (2 papers, 2021 to 2024). A major psychotic disorder characterized by abnormalities in the perception or expression of reality. "TFEA for the 122 IFN-γ signature leading-edge subset genes demonstrated that interferon regulated factor 8 (IRF8) is the most likely transcription factor candidate driving the enrichment of this signature in schizophrenia." (PMID 34054608, 2021).
skin cancer (2 papers, 2020 to 2023). "Our results show that a marked correlation between the CD103+DC signature (IRF8, FMS‐like tyrosine kinase 3 ligand, CLEC9A, CLNK, XCR1, BATF3, and ZBTB46) and chemokines C‐X‐C motif chemokine ligand 9, CXCL10, and CD8A in a mouse model with DMBA/TPA‐induced skin cancer." (PMID 36891351, 2023).
soft tissue sarcoma (2 papers, 2014 to 2017). A malignant neoplasm arising from muscle tissue, adipose tissue, blood vessels, fibrous tissue, or other supportive tissues excluding the bones. "IRF8, which was strongly upregulated in SL4-CXCL16 cells, has been reported to sensitize Fas-mediated apoptosis in soft tissue sarcoma cells and to modulate the metastatic phenotype of CRC by regulating Fas expression." (PMID 25495942, 2014).
toxoplasmosis (2 papers, 2015 to 2022). A parasitic disease contracted by the ingestion or fetal transmission of toxoplasma gondii. "In a model of reactivated toxoplasmosis in ME-49-infected interferon regulatory factor 8-deficient mice, the S+P therapy hampered the onset of toxoplasmic encephalitis and controls brain parasitism." (PMID 35572567, 2022). "Studies in mice have linked several macrophage- or immune-related genes, such as Nramp1/Slc11a1, Icsbp1/Irf8, Csfgm, and Nos2, with the development of several infectious diseases, including salmonellosis, toxoplasmosis, and leishmaniasis." (PMID 26510153, 2015).
type 1 diabetes (2 papers, 2011 to 2025). "Our data reported an enhanced involvement of the IRF4 and IRF8 in DCs function in type 1 diabetes-susceptible NOD mice as opposed to control, nondiabetic mice." (PMID 21647406, 2011).
VKH disease (2 papers, 2017 to 2019). "In summary, the present study shows that hypermethylation of IRF8 in DCs confers risk to VKH disease." (PMID 28432342, 2017). "The results show that hypermethylation of IRF8 confers risk to VKH disease." (PMID 28432342, 2017). "In Vogt-Koyanagi-Harada disease (VKH), monocyte-derived dendritic cells (MDDCs) from active VKH patients have decreased IRF-8 mRNA expression in association with higher methylation levels compared with normal controls or individuals with inactive VKH." (PMID 31849969, 2019). "We found that the drug treatment affected the activity of VKH disease, and the methylation level of IRF8 showed significant differences between active and inactive patients." (PMID 28432342, 2017). "Targeting methylation of IRF8 gene promoter sites may provide a promising therapeutic target protect against VKH disease." (PMID 28432342, 2017). "Nevertheless, how these conventional drugs used for the treatment of VKH disease affect the methylation change and expression of IRF8 remains unknown." (PMID 28432342, 2017). "Demethylation of IRF8 may offer a novel therapeutic strategy protect against VKH disease." (PMID 28432342, 2017). "Moreover, the changes observed in IRF8 may coincide with one or more inflammatory factors operative in the frame of VKH disease pathogenesis and a more (genome wide) systematic approach is necessary to improve our understanding of the pathology of this disease." (PMID 28432342, 2017).
allergic asthma (1 paper, 2023). A asthma with a basis in a pathological type I hypersensitivity reaction. "Whereas the Xcr1+ Irf8+Batf3+ cDC1 showed similar frequencies in all experimental conditions, Xcr1-Irf8+Batf3+ cDC1 frequencies were elevated in the allergic asthma model compared to the allergen tolerance model and controls." (PMID 37251386, 2023). "In order to understand functional differences between Xcr1+Irf8+Batf3+ cDC1 and Xcr1- Irf8+Batf3+ cDC1 clusters, we assessed differential gene expression in allergen-naïve control mice that had not been referred to the allergic asthma model or allergen tolerance model." (PMID 37251386, 2023).
Allergy (1 paper, 2023). An allergy is an immune response or reaction to substances that are usually not harmful. "We identified the well-known Xcr1+Irf8+Barf3+ cDC1 cluster as well as an Xcr1-Irf8+Batf+ cDC1 cluster which was present in allergen-naïve control mice and which expanded at least in frequencies during type-2 inflammation induced in a murine allergy model." (PMID 37251386, 2023).
anaplastic large cell lymphoma (1 paper, 2023). Anaplastic large cell lymphoma (ALCL) is a rare and aggressive peripheral T-cell non-Hodgkin lymphoma, belonging to the group of CD30-positive lymphoproliferative disorders, which affects lymph nodes and extranodal sites. "A study conducted an evaluation of IRF8 expression in CHL (74 cases), NLPHL (seven cases), ALK-negative anaplastic large cell lymphoma (ALCL) (15 cases), and ALK-positive ALCL (four cases)." (PMID 38179383, 2023).
Anxiety (1 paper, 2025). Intense feelings of nervousness, tension, or panic often arise in response to interpersonal stresses. "Here, we show that IRF8 deficiency drives anxiety-like and repetitive disorders in mice in a sex-dependent manner, with female mice exhibiting more severe symptoms." (PMID 40950089, 2025). "Examination of conditional knock out mice revealed that IRF8 confers protection against anxiety during the prenatal stage." (PMID 40950089, 2025). "A battery of behavioral tests revealed that female IRF8 knockout (IRF8KO) mice show increased anxiety relative to male IRF8KO and wild-type mice." (PMID 40950089, 2025). "To investigate at which stage IRF8 affects anxiety-related behavior, we examined conditional IRF8 knockout (IRF8cKO) mice, where IRF8 was deleted postnatally upon Tamoxifen injection." (PMID 40950089, 2025). "In sum, this work demonstrates that IRF8 in microglia plays a major role in controlling anxiety in a sex dependent manner." (PMID 40950089, 2025). "Using a series of anxiety-avoidant tasks, we found that mice without IRF8 display anxiety disorder-like behavior." (PMID 40950089, 2025). "The absence of IRF8 likely prevents the formation of neuronal connections important for handling stress and anxiety." (PMID 40950089, 2025). "However, deletion of IRF8 after birth did not cause anxiety-like behavior, nor OCD, indicating that IRF8 sets proper neuronal connections during the prenatal stage to control anxiety." (PMID 40950089, 2025).
anxiety disorder (1 paper, 2025). A category of psychiatric disorders which are characterized by anxious feelings or fear often accompanied by physical symptoms associated with anxiety. "In summary, we show that IRF8, a transcription factor expressed in microglia, influences the development of anxiety disorders in a sex dependent manner." (PMID 40950089, 2025). "Here, we investigated the role of IRF8 in anxiety disorders in the mouse model." (PMID 40950089, 2025).
Ataxia (1 paper, 2022). Ataxia refers to impaired coordination of voluntary muscle movement. "All infected Irf8‒/‒ mice developed discrepant lethargy and ataxia within 5 days of HSV-1 infection and died within 2 days after the appearance of symptoms." (PMID 35973990, 2022).
autoimmune thyroiditis (1 paper, 2022). "The IRF-8 polymorphism, rs17445836, was associated with both development of autoimmune thyroiditis and TB." (PMID 36078039, 2022).
blood disease (1 paper, 2022). A disease that occurs in the blood. "IRF-8 expression profoundly affects pathogenic processes ranging from infections to blood diseases." (PMID 35211408, 2022).
bone marrow disorder (1 paper, 2023). Any disease of the bone marrow. "Identifying Irf8 effectors may define mediators of both events and thus contributors to age-related bone marrow disorders." (PMID 37247756, 2023).
breast tumor (1 paper, 2020). "Moreover, downregulation of IRF8 was evident in breast tumor conditions leading to the progression of disease." (PMID 32984004, 2020).
choroidal neovascularization (1 paper, 2022). An eye disorder described by the growth of new blood vessels that originate from the choroid through a break in the Bruch membrane into the sub–retinal pigment epithelium (sub-RPE) or subretinal space. "IRF8 was recently reported to play a critical role in retinal microglial homeostasis in steady state and microglial reactivation in laser injury, which negatively impacts choroidal neovascularization (CNV), leading to reduced CNV size." (PMID 36498991, 2022).
chronic kidney disease (1 paper, 2023). Impairment of the renal function secondary to chronic kidney damage persisting for three or more months. "Hence, conclusions on disorders of immune cell populations and IRF8 expression in patients with chronic kidney disease without KRT cannot be fully extrapolated from our results derived from patients with KFRT." (PMID 37508555, 2023).
cognitive decline (1 paper, 2019). "Similarly, correlations of non-classical monocyte expression of IRF-8 with cerebral white matter volume, working memory, executive function, and global NP performance are in line with the literature relating white matter reductions to cognitive decline." (PMID 31849969, 2019).
complication (1 paper, 2022). Any disease or disorder that occurs during the course of, or because of, another disease, treatment, or procedure. "Furthermore, SQC also modulated the miR-223-3p/RBP-J/IRF8 axis in the macrophages of rats with diabetic thoracic aortic complications." (PMID 36212957, 2022). "Taken together, the findings of this study showed that SQC reduced diabetic thoracic aortic complications by modulating apoptosis, oxidative stress, and the inflammatory microenvironment via the miR-223-3p/RBP-J/IRF8 axis." (PMID 36212957, 2022).
Crohn disease (1 paper, 2017). A gastrointestinal disorder characterized by chronic inflammation involving all layers of the intestinal wall, noncaseating granulomas affecting the intestinal wall and regional lymph nodes, and transmural fibrosis. "Notable genes with VDR binding included PTPN2 associated with Crohn’s disease and T1D, and IRF8, which was associated with MS45." (PMID 28377587, 2017).
cystic fibrosis (1 paper, 2022). Autosomal recessive disorder caused by pathogenic variants in the CFTR gene (cystic fibrosis transmembrane conductance regulator), which encodes a chloride and bicarbonate channel expressed in epithelial cells, and follow the diagnosis criteria. "Cystic fibrosis mice exhibit a constitutive decrease of sphingosine in bronchial epithelial cells, which is caused by an IRF-8-regulated down-regulation of acid ceramidase expression in Cftr-deficient bronchial epithelial cells." (PMID 35862397, 2022).
cytomegalovirus infection (1 paper, 2019). A herpesvirus infection caused by Cytomegalovirus. "Moreover, IRF8 is crucial for NK-cell-mediated immunity against mouse cytomegalovirus infection." (PMID 31684858, 2019).
demyelination (1 paper, 2012). "Defective scavenging activity of IRF8-deficient microglia was further confirmed in vivo in the cuprizone-induced demyelination model in mice." (PMID 23020843, 2012). "Microglial response in vivo was compared between wild-type and IRF8-deficient mice in the cuprizon-induced demyelination model." (PMID 23020843, 2012). "Defective scavenging activity of Irf8-/- microglia was also observed in our in vivo experiment using the cuprizone-induced demyelination model." (PMID 23020843, 2012).
emphysema (1 paper, 2023). "In contrast, the downregulated TFs (Mafb, Tead1, Irf8, and Runx3) had the lowest regulatory activity in module 4 of the PPE-induced emphysema model." (PMID 37816708, 2023).